UNC13C (unc-13 homolog C)
Description:
May play a role in vesicle maturation during exocytosis as a target of the diacylglycerol second messenger pathway. May be involved in the regulation of synaptic transmission at parallel fiber - Purkinje cell synapses (By similarity).
Synonyms: Munc13-3; DKFZp547H074
Tractability: Antibody: UniProt places it where antibodies can reach, with medium confidence; its Gene Ontology location is reachable by antibodies, with medium confidence. PROTAC: ubiquitination databases record sites on it.
Gene: Protein-coding gene on chromosome 15 (53,978,201 to 54,628,707, forward strand). Ensembl gene ENSG00000137766.
Subcellular location: Cytoplasm; Membrane; Presynaptic cell membrane
Subcellular location (Human Protein Atlas): Vesicles; Cytosol
Gene Ontology:
Molecular function: calmodulin binding; syntaxin-1 binding; calcium ion binding; diacylglycerol binding; phospholipid binding
Biological process: chemical synaptic transmission; dense core granule priming; synaptic transmission, glutamatergic; synaptic vesicle priming; negative regulation of synaptic plasticity; synaptic vesicle exocytosis
Cellular component: neuromuscular junction; plasma membrane; presynaptic active zone; presynaptic membrane; synaptic vesicle membrane; terminal bouton; calyx of Held; cytoplasm; membrane; parallel fiber to Purkinje cell synapse; presynapse
Genetic constraint (gnomAD): Loss-of-function variants: 138 observed, 185.57 expected, observed/expected ratio (o/e) 0.74, 90% interval 0.65 to 0.86. The upper end of that interval is the gene's LOEUF score, 0.86, which puts it in group 3 of 6, group 1 being the genes least tolerant of losing a copy. Missense variants: 2,548 observed, 2,366.7 expected, observed/expected ratio (o/e) 1.08, 90% interval 1.04 to 1.11. Synonymous variants: 893 observed, 826.7 expected, observed/expected ratio (o/e) 1.08, 90% interval 1.02 to 1.14.
Homologues: Orthologues: chimpanzee UNC13C (99% identical), macaque UNC13C (98% identical), dog UNC13C (95% identical), pig UNC13C (94% identical), rabbit UNC13C (94% identical), mouse Unc13c (91% identical), rat Unc13c (91% identical), guinea pig UNC13C (89% identical), tropical clawed frog unc13c (76% identical), zebrafish unc13c (18% identical). Paralogues in human: UNC13B (49% identical), UNC13A (45% identical).
Diseases named in the same sentence as UNC13C in open-access papers:
UNC13C is named in the same sentence as 29 diseases in open-access papers, as found by Europe PMC text mining. Sharing a sentence is not in itself a finding about the gene and the disease. The quoted sentences say what the papers report.
oral squamous cell carcinoma (5 papers, 2019 to 2025). "UNC13C is implicated in oral squamous cell carcinoma (OSCC) and hepatocellular carcinoma (HCC), and has a neuroprotective role in Alzheimer's disease (AD)." (PMID 38188011, 2023). "Although less studied compared to its counterparts, UNC13C has been implicated in several disease states such as oral squamous cell carcinoma (OSCC) and hepatocellular carcinoma (HCC)." (PMID 38188011, 2023). "UNC13C is one of a family of proteins with key roles in exocytosis and has been reported to downregulate tumor progression in oral squamous cell carcinomas through its role in regulating epithelial-to-mesenchymal transition (EMT) signaling pathways." (PMID 40229280, 2025). "Aberrant expression of UNC13C (Unc-13 Homolog C) has been observed during the progression of oral squamous cell carcinoma." (PMID 37575271, 2023). "Potential function of UNC13C in variety of cancers including, oral squamous cell carcinoma (OSCC) remains obscure." (PMID 31440468, 2019).
head and neck cancer (2 papers, 2020 to 2025). A primary or metastatic malignant neoplasm affecting the head and neck. "While UNC13C and STEAP4 mutations have been found human head and neck cancers, their role in oral carcinogenesis remains unclear." (PMID 32131500, 2020).
hepatocellular carcinoma (2 papers, 2023). A malignant tumor that arises from hepatocytes. "Further studies with larger sample sets are needed to understand the clinical implications of UNC13C in hepatocellular carcinoma." (PMID 37575271, 2023). "However, the expression pattern and clinical relevance of UNC13C in Hepatocellular carcinoma (HCC) remain to be elucidated." (PMID 37575271, 2023).
Alzheimer's dementia (1 paper, 2023). "Moreover, UNC13C is believed to be a protective gene against disease progression in Alzheimer's dementia (AD)." (PMID 38188011, 2023).
amyotrophic lateral sclerosis (1 paper, 2022). Amyotrophic lateral sclerosis (ALS) is a neurodegenerative disease characterized by progressive muscular paralysis reflecting degeneration of motor neurons in the primary motor cortex, corticospinal tracts, brainstem and spinal cord. "Unc13c was significantly down-regulated in spinal cord tissues of patients with amyotrophic lateral sclerosis." (PMID 36279395, 2022).
autism (1 paper, 2023). Persistent deficits in social interaction and communication and interaction as well as a markedly restricted repertoire of activity and interest as well as repetitive patterns of behavior. "UNC13C's centrality in synaptic transmission adds to the evidence of a potential link directly between CHD and nervous system development and autism which has also been associated with synaptic dysfunction." (PMID 37840956, 2023).
bipolar disorder (1 paper, 2015). A disorder of the brain that causes unusual shifts in mood, energy, activity levels and the ability to carry out day-to-day tasks. "We identified three rare deletions in KCNJ6, UNC13C, OTOL1 and 7 rare duplications in CNTNAP2/MIR548F3, CORO7/VASN, DTNB, EMID2, KCNF1, PDPR and SGTA/THOP1 that are present in children with bipolar disorder (and their parents)." (PMID 25887117, 2015).
Cirrhosis (1 paper, 2014). A chronic disorder of the liver in which liver tissue becomes scarred and is partially replaced by regenerative nodules and fibrotic tissue resulting in loss of liver function. "In addition, KIF5C, MYH8, SETD2 and UNC13C mutations were only found in HCC patients in the absence of cirrhosis (0% vs. 11%, p = 0.036 for all four genes)." (PMID 24988079, 2014).
genetic dementia (1 paper, 2022). "Unc13c has also been found to be associated with neurodegeneration in a genetic dementia in Finland." (PMID 36279395, 2022).
latent infection (1 paper, 2025). "The downregulated DETs of Sept4, Kcng4, Unc13c, and Prkcg in the WH6 group, which are related to synaptic transmission, and Ndrg2 and Arc in the LHG group, which are related to neurodegenerative diseases, were selected to be the key candidates in the latent infection phase." (PMID 40420177, 2025).
metabolic syndrome (1 paper, 2022). A cluster of metabolic risk factors for CARDIOVASCULAR DISEASES and TYPE 2 DIABETES MELLITUS. "In the metabolic syndrome sub-network, five genes had high degrees of connection and could be considered hub genes: PTPRD, DCC Netrin 1 Receptor (DCC), Proprotein Convertase Subtilisin/kexin Type 6 (PCSK6), Unc-13 Homolog C (UNC13C), and Contactin 4 (CNTN4)." (PMID 35121771, 2022).
oral cancer (1 paper, 2019). "UNC13C is predicted in regulating neurotransmitter release; alterations in UNC13C could be associated to predisposition to tobacco addiction, which might enhance the risk of oral cancer." (PMID 31440468, 2019). "We observed that UNC13C overexpression in oral cancer cells down regulated cellular migration and invasion and undergo a morphologic change like EMT." (PMID 31440468, 2019). "The importance of the EMT in UNC13C-related metastatic functions of oral cancer needs further research." (PMID 31440468, 2019). "We also identified decreased overall UNC13C expression in oral cancer cell lines." (PMID 31440468, 2019). "Additionally, we investigated the possible roles and molecular mechanisms of UNC13C in oral cancer cells using in vitro models." (PMID 31440468, 2019). "For validating the role of UNC13C in EMT pathway in vitro, oral cancer cells analyzed for migration and invasion ability." (PMID 31440468, 2019). "In summary, these results suggest that UNC13C as a novel tumor suppressor and an essential regulator of EMT signaling pathway during OSCC progression, and thus it could be used as a target for preventing oral cancer metastasis." (PMID 31440468, 2019).
tumor (10 papers, 2019 to 2026). "Analysis of somatic mutation spectra revealed five novel variants in different genes, including a potentially deleterious variant in UNC13C that was common for the tumor and metastasis." (PMID 37175927, 2023). "It was unclear what role UNC13C played in tumor pathogenesis or whether a deficiency could be associated with the predisposition to nicotine addiction and tobacco use in OSCC." (PMID 38188011, 2023). "UNC13C plays a role in tumor suppression in the pathogenesis of OSCC and an oncogenic role in the pathogenesis of HCC." (PMID 38188011, 2023). "Correlation analysis suggested that the mRNA level of UNC13C was negatively correlated with miR-96-5p level in OSCC tumor tissues." (PMID 33715625, 2021). "It is well-known that epithelial–mesenchymal transition (EMT) is an important event involved in the initiation of tumor invasion; the impact of UNC13C on the expression of EMT markers was analyzed in SCC-9 and SAS cells." (PMID 31440468, 2019). "Furthermore, we developed a prognostic nomogram based on IMPG2, BNC2, PAPPA2, ITGBL1and UNC13C expression levels in tumor cells to predict survival outcomes." (PMID 42157926, 2026). "Moreover, UNC13C silencing has been shown to repress the activity of the miR-96-5p inhibitor, resulting in lowered apoptotic tendency and susceptibility to radiotherapy in OSCC cells, further establishing the role of UNC13C in tumor suppression." (PMID 38188011, 2023). "UNC13C overexpression was shown to repress key proteins required for the epithelial-mesenchymal transition, which is a critical process in early tumor cell migration and metastasis, suggesting that UNC13C may directly act as a tumor suppressor." (PMID 38188011, 2023). "UNC13C overexpression in tumours could be a potential biomarker for prognosis and a potential target for therapy." (PMID 37575271, 2023). "Animal experiments revealed that circ-KIAA0907 could reduce the tumor growth of OSCC by regulating the miR-96-5p/UNC13C axis." (PMID 33715625, 2021). "Transcription factors like NOTCH1 (16%) and KMT2B (16%), UNC13C (14%), another tumor suppressor, ERCC2 (14%) involved in nucleotide excision repair pathway, were recurrently mutated, whereas genes like CDKN2A, MLH1, FGFR1, EGFR, etc. had a less than 10% mutation frequency." (PMID 34796107, 2021). "All of these data indicate that UNC13C acts as a tumor suppressor in OSCC and that the downregulation of UNC13C may promote progression and metastasis of OSCC." (PMID 31440468, 2019). "Our study provides novel insights into the tumor suppressive role of UNC13C in OSCC, restoring UNC13C expression may be a novel treatment strategy for OSCC." (PMID 31440468, 2019). "However, further research has indicated that tumor cell lines in OSCC patients express UNC13C at significantly lower levels than surrounding healthy tissue, with low expression levels also being correlated with poor prognosis for survival in this patient population." (PMID 38188011, 2023). "In addition, the mutation frequencies of UNC13C, PIKfyve, and CAPN9 were significantly different between EUR and AFR (p < 0.05) and might affect prognosis by regulating tumor proliferation and apoptosis." (PMID 34950653, 2021). "However, the function of UNC13C in tumor initiation and progression is unclear." (PMID 31440468, 2019). "Unc-13 homolog C (UNC13C), a member of the Unc/Munc family is involved in aspects of cancer progression such as tumour development, cell migration 10, and metastasis." (PMID 37575271, 2023). "UNC13C expression was evaluated and scored by two pathologists, tumor tissues showed positive and negative staining of UNC13C." (PMID 31440468, 2019).
cancer (7 papers, 2018 to 2025). A tumor composed of atypical neoplastic, often pleomorphic cells that invade other tissues. "Decreased E-cadherin expression plays an important factor in cancer metastasis, however in our study UNC13C expression was negatively associated with E-cadherin expression in both SCC9 and SAS cell lines." (PMID 31440468, 2019). "The anti-cancer role of UNC13C in OSCC was confirmed in our research, which was consistent with the previous study." (PMID 33715625, 2021). "In OSCC cancer tissues, we found that UNC13C mRNA expression was positively correlated with circ-KIAA0907 expression." (PMID 33715625, 2021). "The expression of UNC13C in HCC cancer tissue was examined by IHC staining." (PMID 37575271, 2023). "Tobacco related genes, such as USP9X, ARID2, MLL4, TRPM3 and UNC13C, exactly showed no mutations in buccal mucosal cancer cell lines with no risk-habits of tobacco smoking or chewing." (PMID 36611830, 2022). "Besides, we discovered that UNC13C was lowly expressed in OSCC cancer tissues at the mRNA level and protein level." (PMID 33715625, 2021). "Significantly decreased UNC13C mRNA and protein expression in OSCC cell lines was also reproduced in a study on the protein's anti-cancer effects." (PMID 38188011, 2023).
neurological disorder (2 papers, 2023 to 2025). "Additionally, GPN-MSA_SCORES for the following variants indicated high pathogenic potential: PCDHB11I (−9.39), GAB4RA1 (−8.55), and UNC13C (−7.9), all of which have been previously associated with neurological disorder-related phenotypes." (PMID 40282380, 2025).
infection (1 paper, 2025). The state of being infected such as from the introduction of a foreign agent such as serum, vaccine, antigenic substance or organism. "In our study, downregulation of UNC13C may reflect impaired tissue morphogenesis during infection." (PMID 40943072, 2025).
neurodevelopmental disorder (1 paper, 2026). A behavioral and cognitive disorder with onset during the developmental period that involves impaired or aberrant development of intellectual, motor, or social functions. "•Eleven patients with neurodevelopmental disorders carry rare UNC13C variants." (PMID 41399760, 2026).
UNC13C also shares sentences with these, for which no sentence is quoted: Alzheimer's disease (1 paper); Anxiety (1); Aphasia (1); cognitive deficit (1); epilepsy (1); medulloblastoma (1); melanoma (1); neurodegenerative disease (1); Oculomotor apraxia (1); Parkinson disease (1); type 2 diabetes (1); vascular malformation (1).